FASN (fatty acid synthase)
Diseases named in the same sentence as FASN in open-access papers (continued):
Sharing a sentence is not in itself a finding about the gene and the disease.
tumor (continued). "Some metastatic tumours have significantly lower FASN expression than their corresponding primary tumours, allowing them to metabolically adapt to the different environments at their respective metastatic site, probably different from that of their primary site." (PMID 35448537, 2022). "The volcano plot further indicates that FASN was significantly upregulated in tumor tissues." (PMID 35392075, 2022). "For instance, FASN absence in T reg cells can prevent tumor cell proliferation." (PMID 36555243, 2022). "Similarly, LMP1 induces sterol response element binding protein 1 (SREBP1) in NPCs to up-regulate FASN and promote tumor progression, and LMP1 and FASN levels correlate in primary NPC samples." (PMID 35108325, 2022). "In KIRP (p < 0.001), KIRC (p < 0.001), TGCT (p < 0.01), adrenocortical carcinoma (ACC, p < 0.05), BRCA (p < 0.05), and CESC (p < 0.05), the expression of FASN was increased with the stage of tumor progression and was negatively correlated only in OV (p < 0.01)." (PMID 36555243, 2022). "By immunohistochemistry, tumor cells were positive for vimentin, S100, FASN, CD10, and p16." (PMID 36619259, 2022). "FASN inhibition may have a notable effect on altering the expression of key proteins, which may influence tumor progression and migration." (PMID 35566090, 2022). "We also found that the expression of FASN was significantly correlated with the tumor size." (PMID 35350838, 2022). "TPM3, CHMP4C, EEF1A1, FASN, TNF, S100A10, and IL1A represent a high-risk score and poor prognosis, suggesting that these genes may be associated with the tumor process in patients with CC and appear to be pro-oncogenes." (PMID 36685937, 2022). "This further indicated that FASN is involved in the interaction between tumor cells and immune cells, and the high expression of FASN may play a biological role in anti-tumor immunity in various tumors." (PMID 36555243, 2022). "Furthermore, the tumor stage results further demonstrated that FASN is involved in the regulation of tumor progression." (PMID 36555243, 2022). "We used the mirDB, TargetScan, ENCORI, and mirDIP databases to identify the miRNAs that may target FASN and verified the tumor suppressor effect of mir-195-5p targeting FASN in HCC." (PMID 36555243, 2022). "Moreover, orlistat, an irreversible inhibitor of FASN, was shown to reduce tumor lung metastases (53.4%) in C57BL/6 mice subcutaneously injected with melanoma B16-F10 cells." (PMID 34150624, 2021). "Tumor cells rely more on de novo lipid synthesis rather than utilization of exogenous lipids, and high levels of FASN are associated with poor prognosis." (PMID 33803184, 2021). "FASN has previously been shown to be responsible for high tumor related lymphangiogenesis." (PMID 34831316, 2021). "FASN expression was found to be higher in most tumor tissues than contrast tissues." (PMID 34879004, 2021). "Interestingly both FASN and ACLY were significantly upregulated in the four BCa patients’ datasets that we interrogated and the expression of FASN positively correlated with tumor aggressiveness, advanced grade and stage, and poor prognosis." (PMID 34764423, 2021). "Additionally, the downregulation of SNHG25, overexpression of miR-497-5p, and reduction of FASN were confirmed in sh-SNHG25-transfected tumor xenografts." (PMID 34789312, 2021). "TVB-3664, a novel FASN inhibitor, showed its anti-tumor effect in CRC." (PMID 34200820, 2021). "Synthetic upregulation miR-33a might furthermore show its tumor-suppressor role through inhibiting fatty acid synthase metabolism." (PMID 34771486, 2021). "Tumors with PTEN loss had higher Gleason grades and more advanced tumor stage irrespective of FASN expression." (PMID 33166087, 2021).
tumor (continued). "Previous studies have established the anti‐tumour effects of the first‐generation FASN inhibitors." (PMID 33626208, 2021). "In our previous studies, we found that inhibition of FASN expression by orlistat could suppress tumor growth in both HT-29/tk-luc and LNCaP/tk-luc tumor-bearing mouse models." (PMID 33974005, 2021). "The level of FASN in tumor tissues is higher than that in adjacent tissues." (PMID 34620841, 2021). "Notably, the expression levels of both MAOB and LRP1 were downregulated in tumor samples compared with normal samples in the TCGA and GEO databases, but the expression of FASN was upregulated." (PMID 34819038, 2021). "Finally, we showed for the first time that induction of SREBP‐1 and its target gene, FASN, plays a key role in the tumor‐promoting effects of leptin." (PMID 33226729, 2021). "A FASN-specific inhibitor can effectively promote apoptosis of tumor cells." (PMID 33789749, 2021). "Targeting FASN upregulation of the tumor-promoting pathway can enhance anti-tumor immunity." (PMID 33732237, 2021). "Past studies have verified that FASN overexpression promoted the occurrence, development and metastasis of tumor cells, which may be a biomarker for many tumors to produce malignant phenotypes and poor prognosis." (PMID 34790227, 2021). "Besides FASN, other enzymes involved in the de novo synthesis of fatty acids also showed tumor-promoting activity in CRC, making them reasonable targets for therapy." (PMID 34200820, 2021). "Since enzalutamide and ADT are frequently used for the treatment of PCa, the present study aimed to unravel the underlying mechanism of combination of orlistat, an FASN inhibitor, and enzalutamide using PC3 cell line; and orlistat and castration in PC3 tumor-bearing animal model." (PMID 33974005, 2021). "Study showed that downregulation of FASN production caused apoptosis in tumor cells rather than normal cells." (PMID 34620841, 2021). "FASN regulates tumor angiogenesis by altering secretion and activity of VEGF." (PMID 34040635, 2021). "In this respect, the first human study of FASN inhibitor (TVB-2640) monotherapy in advanced tumours showed a disease control rate of 42% (29/69) compared to 70% (37/53) in combination with paclitaxel and exhibited an 11.8% partial response rate in the OC group." (PMID 34944851, 2021). "FASN overexpression is closely related to the degree of malignant tumor progression." (PMID 33718168, 2021). "Finally, FASN levels in serum were also examined in CRC patients, where it was associated with tumor stage, and high FASN levels are considered as a promising independent predictor of CRC with advanced phases, late clinical stages, and shorter survival." (PMID 33194695, 2020). "FASN silencing in cancer cells decreases LDs in DCs, consequently increasing infiltrative T cells and delaying tumor growth, which suggests that tumor cell lipogenesis could be involved in anticancer immunity." (PMID 32029741, 2020). "Overall, our data indicate that elevated levels of both active c-MYC and FASN gene are predictors of poor prognosis in this aggressive tumor, and suggest the functional interplay between c-MYC and FASN also in human HCC, as demonstrated in in vitro and in vivo models." (PMID 33187130, 2020). "Moreover, a significant association was shown between FASN and VEGF expression, suggesting the involvement of FAS in tumor angiogenesis." (PMID 33194695, 2020). "The increase in fatty acid synthesis in tumor cells is indicated by a significant elevation in the expression and activation of a number of enzymes functioning in the lipogenic pathway, one of which is fatty acid synthase (FASN)." (PMID 33112541, 2020). "In addition, IHC of tumour samples revealed an increasing trend of FASN expression in the gemcitabine treatment group, while FASN expression was repressed in the α‐mangostin and gemcitabine combination treatment group." (PMID 31762191, 2020).
tumor (continued). "Importantly, in vivo treatment with the FASN inhibitor C75 notably restored the anti-tumor activity of tamoxifen and fulvestrant against fast-growing, hormone-resistant MCF-7/HRG xenograft tumors in mice." (PMID 33081219, 2020). "This suggests the involvement of other oncogenic signaling pathways that may uncouple nutrient sensors from regulating FASN in tumor cells." (PMID 32872164, 2020). "Specifically, while tumors rapidly emerged in the liver parenchyma of c-Myc/MCL1 wild-type mice, resulting in high tumor burden by 5-6 weeks post hydrodynamic injection, a comparable tumor burden was observed only 36 weeks post injection in c-Myc/MCL1 mice depleted of FASN (c-Myc/MCL1/Cre mice)." (PMID 33187130, 2020). "MiR-320 inhibited tumor progression by targeting FASN in NSCLC." (PMID 33050166, 2020). "In human HCC, expression of major enzymes associated with de novo lipogenesis, including FASN, is increased in tumor lesions compared with liver non-neoplastic counterparts." (PMID 32947972, 2020). "Fatty acid synthase (FASN) has been found to be overexpressed in TNBC tumor cells." (PMID 32296646, 2020). "The xenograft mouse model was used to evaluate tumor weights after suppression of FASN." (PMID 31122252, 2019). "G28 displayed a potent tumor volume reduction in vivo with no weight loss or anorexia, the main side-effects of other FASN inhibitors like the cerulenin-derived compound C75." (PMID 30875891, 2019). "An alternative approach to suppress FASN in HCC (and other tumor types) could be the inhibition of FASN upstream inducers, such as USP2a and CD147." (PMID 31921669, 2019). "Indeed, many studies reported an enhanced FASN activity in tumor progression, accompanied by an increase of desaturase activity, although this latter process is not observed in our animal model." (PMID 30987375, 2019). "Our results are in agreement with earlier researches that intrinsic pathway involvement in apoptosis, as evidenced by changing the expression of caspase family and Bcl-2 family members, has been found in several tumor cell lines following pharmacological FASN inhibition." (PMID 30824767, 2019). "Therefore, to further study the roles of FASN in suspended tumor cells, we used lentivirus method to infect the cells." (PMID 30931932, 2019). "The xenograft tumor model was used to determine the effect of FASN inhibition in NSCLC progress." (PMID 31122252, 2019). "Taken together, these data suggest that in the absence of FASN, citrate lyase activity is diminished, and this enzymatic impairment is linked to a defect in 3D, but not 2D, tumor cell growth." (PMID 31676791, 2019). "Moreover, LOX-1 was found expressed with a different intensity and localization also in Luminal A (ER+/PR+) and triple negative FASN-expressing tumor." (PMID 30718451, 2019). "In contrast, the FASN inhibitor C75 increased LD levels in tumor cells." (PMID 31835444, 2019). "In addition, a clinical study has shown that EGCG regulates FASN expression and has effects on tumor control." (PMID 31027222, 2019). "Interestingly, pharmacological lipogenesis inhibition with the FASN inhibitor orlistat impaired tumor re-growth and metastasis after sunitinib treatment withdrawal." (PMID 31835444, 2019). "FASN may be an attractive oncology drug target because it is an enzyme readily targeted by small molecule inhibitors, it is differentially expressed in tumor cells, and its sustained activity is needed for tumor growth and survival." (PMID 31681794, 2019). "Moreover, over-expressed FASN also contributes to unfavorable prognoses and treatment resistance in various tumor types, including lung, bladder, prostate, ovarian, osteosarcoma, breast, colorectal, pancreatic and lymphoma." (PMID 31122252, 2019). "FASN activity in tumor-adjacent tissue was much lower than that in the tumor itself." (PMID 31242216, 2019).
tumor (continued). "Moreover, de novo lipogenesis from glycolytic intermediates or acetate via FASN is critical for in vitro self-renewal, and tumor relapse and metastatic dissemination after withdrawal of anti-angiogenic treatment." (PMID 30967773, 2019). "The high-fat diet induces the Akt-FASN activation and promotes tumour progression." (PMID 31527721, 2019). "Even though we did not determine significant correlation between tumor mutational backgrounds and response to FASN inhibition, these findings will be tested in future studies." (PMID 29872506, 2018). "Taken together, our data show that OvCa-cell-intrinsic FASN activation can result in the exclusion of the host immune response, including lipid accumulation in tumor-infiltrating dendritic cells and subsequently the absence of a T-cell infiltrate and dysfunction within the tumor microenvironment." (PMID 30619288, 2018). "A significant decrease in FASN staining in the viable tissue fraction was found in tumours treated with the FASN inhibitor orlistat alone or in combination with cisplatin when compared to vehicle controls (p < 0.0001 for ORL, ORL/CP D0 and p < 0.001 for ORL/CP D2)." (PMID 29569717, 2018). "To evaluate the expression of FASN in a population of patients treated at the University of Kentucky, we analyzed FASN expression in matched normal colon mucosa and tumor tissues from 56 patients with Stage I-IV CRC who had surgery at UK Chandler Medical Center." (PMID 29872506, 2018). "Although the FDA‐approved FASN inhibitor, Orlistat, is shown to be effective in reducing tumor cells in vivo, one main limitation is its extremely low oral bioavailability, as Orlistat exerts its effects primarily in the gastrointestinal tract, where it inactivates pancreatic lipase." (PMID 29449326, 2018). "Moreover, FASN staining was also reduced in the ORL/CP D0‐treated tumours when compared to cisplatin‐treated (CP D0) tumours (p < 0.0001)." (PMID 29569717, 2018). "Furthermore, EGFR signaling through Akt increases the demand of EGFR mutant cells for fatty acid synthesis, resulting in the upregulation of FASN and rapid division of tumor cells." (PMID 29449326, 2018). "FASN expression in OvCa directly promotes tumorigenesis, however, whether it also creates a tumor-permissive immune milieu is unknown." (PMID 30619288, 2018). "Then, we sought to determine whether FASN might drive tumor growth by inhibiting DCs-dependent anti-tumor immunity." (PMID 30619288, 2018). "FASN is involved in de novo FA synthesis pathways by elongating of FAs and producing FA palmitate from acetyl-CoA, which is required for cell malignant transformation and tumor formation." (PMID 30233549, 2018). "The results showed that upregulation of lipid accumulation in TIDCs characterized by defective profiling with impaired priming of anti-tumor T cells, which results from an increased uptake of lipids found at high concentrations in the tumor microenvironment with high FASN expression." (PMID 30619288, 2018). "On the other hand, epigallocatechin-3-gallate (EGCG), the main polyphenolic catechin of green tea, has been described to inhibit FASN, to induce apoptosis in vitro and to reduce tumor size, without parallel CPT-1 stimulation or weight loss." (PMID 29751678, 2018). "Furthermore, inhibiting FASN activity alone or in combination with PI3K inhibitors demonstrated a robust decrease in tumor growth." (PMID 29483509, 2018). "By inference, tumor-intrinsic FASN activation may represent one mechanism of primary resistance to these therapies." (PMID 30619288, 2018). "However, the role of FASN signaling in driving suppressive tumor microenvironment is less well understood." (PMID 30619288, 2018). "The most frequent tumor grade was III (82.5%) and a negative association between tumor grade and FASN levels was observed." (PMID 29088795, 2017). "FASN was positive in 92% of the tumor tissue samples and 45% of them showed high FASN levels." (PMID 29088795, 2017).
tumor (continued). "First, an increased FASN level in tumor tissues of H157CisR cell-derived xenografts were detected compared to tissues of H157P cell-derived xenografts, confirming the in vitro result showing an increased FASN level in cisplatin-resistant cells compared to parental cells." (PMID 27765901, 2016). "The HFD promoted tumour growth and FASN expression in the LNCaP xenograft mice." (PMID 26878389, 2016). "FASN synthesizes long-chain fatty acids, mainly palmitate, and has a major role in the synthesis of phospholipids required for newly synthesized cellular membranes in highly proliferating tumor cells." (PMID 26808816, 2016). "However, in tumor cells, [11C]acetate is incorporated into membrane lipids due to over-expression of fatty acid synthase (FASN)." (PMID 26973812, 2016). "As anticipated, tumor-derived cells from CA1d control lesions generated fast growing tumors, whereas tumor-derived cells from FASN-depleted lesions continued to form very small, slowly growing lesions that remained dormant for more than 30 days after injection." (PMID 27223424, 2016). "FASN inhibition with chemical inhibitors or RNAi can suppress tumour cell survival." (PMID 27357947, 2016). "FASN makes an attractive therapeutic target as it appears to be upstream of multiple neoplastic transformations and metastasis as well as angiogenic pathways manipulating tumor vascularity and cell proliferation." (PMID 27270654, 2016). "In addition, serum FASN levels were inversely correlated with tumour volumes (total, r=0.642, P=0.022; HFD group, r=−0.618, P=0.024; LFD group, r=−0.439, P=0.154)." (PMID 26878389, 2016). "Moreover, the serum FASN level was inversely correlated with tumour growth in LNCaP xenograft mice under HFD conditions." (PMID 26878389, 2016). "Gansler TS deemed that FASN was an independent prognostic indicator for tumor." (PMID 25433947, 2015). "With respect to lipid metabolism, inhibition of FASN has been reported to inhibit tumor growth." (PMID 26334757, 2015). "Levels of FASN expression increased with tumor dedifferention (50% of G1 to 80% of G4 tumors)." (PMID 25948777, 2015). "Especially, EC frequently overexpress FASN, whereas SEM and tumor-free testes express FASN rarely." (PMID 26377566, 2015). "In addition, several FASN inhibitors have been shown to decrease tumor cell growth or increase tumor cell death." (PMID 25751270, 2015). "Also, we showed marked FASN overexpression at the mRNA level by qRT-PCR and at the post-transcriptional level by WB in cell lines as well as primary tumor cultures of varying degrees of chemoresistance and differentiation." (PMID 25947066, 2015). "Moreover, the tumor tissues from mice in GA group exhibited low level of FASN staining compared with that from mice in Control group." (PMID 25895130, 2015). "FASN inhibitors cerulenin and C75 induce cell cycle arrest and apoptosis in tumor cells." (PMID 25978957, 2015). "When comparing expressions of lipid metabolism—related proteins among molecular subtypes, the expression of PLIN1 (p < 0.001), FABP4 (p = 0.029), CPT-1A (p = 0.001), ACOX-1 (p < 0.001), and FASN (p < 0.001) differed significantly among the different tumor subtypes." (PMID 25751270, 2015). "Moreover, consumption of CAPE or CAPPE also suppressed the expression of malignant biomarker proteins, such as PCNA and FASN in tumor tissues." (PMID 24960186, 2014). "Furthermore, increased FASN expression has a positive relation with tumor aggressiveness and a poor prognosis for renal cell carcinoma." (PMID 24979135, 2014). "Loss of S14 in the MMTV-PyMT model decreased FASN activity and the synthesis of medium-chain fatty acids but did not alter tumor latency." (PMID 25472762, 2014).